CD44 (CD44 molecule (IN blood group))
Diseases named in the same sentence as CD44 in open-access papers (continued):
Sharing a sentence is not in itself a finding about the gene and the disease.
bladder cancer (continued). "The high expression of CD44 in bladder cancer, as a receptor for HA, is directly related to a higher clinical stage, lower treatment response rates, and lower survival rates." (PMID 37111795, 2023). "And the relationship between CD44 expression and macrophage infiltration in bladder cancer needs experimental verification." (PMID 37316699, 2023). "A study showed that bladder cancer cells treated with a CD44 inhibitor had a tendency to reduce the sizes and numbers of tumorospheres, indicating that USP28 can play a vital role in tumor progression by mediating CD44." (PMID 36879346, 2023). "The interaction analysis of the genes that interact with CD44 and bladder cancer-related genes was carried out, and 81 intersection target genes were obtained." (PMID 37316699, 2023). "CD44-positive bladder cancer cells that expressed OCT4 were dramatically increased in bladder cancer cell lines after cisplatin treatment." (PMID 37627900, 2023). "It has been reported that SOX2OT inhibition can restrict the bladder cancer stem cell (CD44+, ALDH1+) self-renewal and cisplatin resistance by SOX2 regulation." (PMID 36548179, 2022). "In this study, we explored the expression levels of CD276 and other bladder cancer stem cell markers including ALDH1, CD24, and CD44 as a function of cellular proliferation on UM-UC bladder cancer cells and NUCs." (PMID 35563359, 2022). "In contrast, a rather strong expression of CD24 was found at least in some areas of bladder cancer samples, but only a few cells expressed CD44 at barely noticeable levels, while CD276 positive cells were found in all samples." (PMID 35563359, 2022). "As both OCS and HA show affinity to selectively bind CD44-expressing cells, self-cross-linkable chitosan-HA dialdehyde nanoparticles are used for CD44-targeted siRNA delivery to target oncogene Bcl2 for bladder cancer therapy." (PMID 36531004, 2022). "Recent animal studies corroborated a low expression of CD44 on 3D bladder cancer organoids, which was upregulated by propagation of the cells in so-called 2.5D organoid constructs in later passages." (PMID 35628262, 2022). "An increased expression of CD44 has been shown to effectively reverse the effects of miR-34a on bladder cancer cell proliferation and chemosensitivity of muscle invasive-bladder cancer cells." (PMID 36685879, 2022). "We therefore investigated the expression of CD276 as well as CD24 and CD44 in lymph node metastases of bladder cancer patients in comparison to bladder cancer samples." (PMID 35563359, 2022). "In a recent study, CD44 has been shown to be targeted by miR-34a in muscle-invasive bladder cancer during cisplatin treatment." (PMID 36685879, 2022). "Of the various isoforms of CD44, the two isoforms, CD44s and CD44v6, have been studied in regard to their roles as biomarkers for bladder cancers, gastric adenocarcinoma, and colorectal adenocarcinoma." (PMID 35626430, 2022). "Others considered the expression of the aldehyde dehydrogenase (ALDH1) paralog A1, or the expression of CD24 and CD44 as bladder cancer stem cell markers." (PMID 35563359, 2022). "There are four types of CSCs markers in bladder cancer, including CD44+, EMA-, 67LR, BCMab1+; they are located in basal cell layer of bladder tumor." (PMID 35903544, 2022). "Similar phenomenon occurs in bladder cancer, so that curcumin administration (0–50 μM) decreases CD44, CD133, ALDH1, Nanog and Oct4 to impair CSC characteristics in bladder cancer and induce apoptosis and proliferation inhibition." (PMID 34769099, 2021). "CD44 emerged as a promising bladder cancer target as its expression correlates with a higher aggressiveness of the tumor defined by a higher invasion ability compared to CD44 negative cells in vitro." (PMID 34123841, 2021). "Among these glycoproteins were MUC16 and CD44, which have already been extensively studied in the context of bladder cancer as part of more aggressive molecular phenotypes." (PMID 34108014, 2021).
bladder cancer (continued). "Next, it is necessary to dissect the mechanisms of NF-ĸB/CD44 signaling in regulating the malignant progression of bladder cancer." (PMID 33573671, 2021). "Among these, NOTCH1, CCND1, CD44, MMP7, TGFR2, and FGFR3 are involved in bladder cancer signaling pathways or are associated with the development of bladder carcinoma." (PMID 33535616, 2021). "We demonstrated that ITPR3 depletion suppressed cancer cell proliferation, migration, invasion and stemness by inhibiting the expression of CD44, which is the main cancer stem cell marker in bladder cancer." (PMID 33573671, 2021). "In conclusion, we demonstrated in this research that ITPR3, as an oncogenic gene, promoted the proliferation, metastasis and stemness of bladder cancer through the NF-κB/CD44 signaling pathway." (PMID 33573671, 2021). "For example, KMP-1 antibody targeting CD44 can inhibit cell division, relocation and adhesion, allowing tumor growth suppression in a mouse model of bladder cancer." (PMID 33889547, 2021). "The current study was first carried out to explore the clinical significance of CD44 expression and its expression on the survival of patients with bladder cancer." (PMID 32434417, 2020). "Making use of a mAb (BCMab1) against CD44+ human bladder cancer cells that recognize aberrantly glycosylated integrin α3β1, we isolated a subset of bladder cancer cells from primary samples in the previous study." (PMID 32065779, 2020). "Bladder cancer stem cells (BCSCs) were isolated from BCCs using flow cytometry based on the stem cell markers CD44 and ALDH1." (PMID 32019566, 2020). "More studies with large sample sizes are essential to further validate the prognostic role of CD44 expression on patients with bladder cancer." (PMID 32434417, 2020). "Ten studies involving 829 patients with bladder cancer assessed the relationships of CD44 expression with clinicopathological characteristics." (PMID 32434417, 2020). "Data involving three studies with 360 bladder cancer patients showed that CD44 expression was significantly correlated with lymph node metastasis (OR = 4.09, 95% CI = 2.20–7.62, P < 0.001)." (PMID 32434417, 2020). "Based on a recent publication, exposure of SFN to bladder cancer cells induced a significant increase of CD44v4 and v7 and diminished chemotaxis, whereby knock-down of CD44 correlated with enhanced chemotaxis." (PMID 33218199, 2020). "We showed that the BCMab1+CD44+ cells act as bladder cancer stem cells (BCSCs) and are correlated with clinicalpathologic features of bladder cancer." (PMID 32065779, 2020). "Self-assembled tumor-targeting HA–IR–780 nanoparticles (HA MW = 10 kDa, and the average size was 171.3 ± 9.14 nm) for PTT in a CD44-over-expressed orthotopic bladder cancer model (MB-49 bladder cancer cells were used) have been developed." (PMID 31835293, 2019). "In conclusion, we generated a novel monoclonal antibody KMP1, which specifically recognized CD44 epitope on bladder cancer cells and had specific antitumor potential both in vivo and in vitro." (PMID 29577645, 2018). "Here, we generated a new mAb KMP1, which specifically recognized CD44 epitope on bladder cancer cells, and the antitumor effects of KMP1 were very clear at three weeks after EJ cells inoculation." (PMID 29577645, 2018). "Immunofluorescence analysis show that treatment with cisplatin enhanced the expression of both CD44 and Oct4 in bladder cancer cells, Notably, CD44 was colocalized with Oct4, suggesting concurrent upregulation of CD44 and Oct4 during cisplatin treatment." (PMID 27244887, 2017). "Nevertheless, the specific glycosylation patterns of CD44 in the context of bladder cancer also remains an open research topic." (PMID 29207682, 2017). "In the present study, we show that CD44-positive cells that expressed Oct4 were dramatically increased in bladder cancer cell lines after cisplatin treatment." (PMID 27244887, 2017).
bladder cancer (continued). "Colocalization between Oct4 and CD44 expression was also observed in the clinical tumor specimens from two patients with bladder cancer." (PMID 27244887, 2017). "CD44-positive cells have been suggested to function as cancer TICs in bladder cancer tissues and bladder cancer cell line T24, which possesses high tumorigenicity and metastatic potential." (PMID 29340052, 2017). "Nevertheless, these alterations can also be significantly observed in other densely O-glycosylated proteins of relevant importance in bladder cancer, namely CD44 and different types of integrins." (PMID 29207682, 2017). "Anchorage dependent and independent proliferation assay showed that loss of both CD44 and RHAMM inhibited growth of bladder cancer cells driven by AGL loss." (PMID 27595989, 2016). "This revealed that bladder cancer cells whose aggressive growth is mediated by loss of AGL are susceptible to apoptosis with loss of HAS2, CD44 or RHAMM." (PMID 27595989, 2016). "Higher amounts of cleaved Cas3, Cas9 and PARP was observed in AGL low bladder cancer cell with loss of HAS2, CD44 or RHAMM." (PMID 27595989, 2016). "Here we explore the role of CD44 and RHAMM in the rapid growth of bladder cancer cells mediated by AGL loss." (PMID 27595989, 2016). "This also provides evidence that CD44 and RHAMM are involved in HAS2/HA signaling in bladder cancer cells with loss of AGL." (PMID 27595989, 2016). "We propose that bladder cancer patients with low AGL expression are an ideal subset of cancer patients who can be treated with CD44 and RHAMM inhibitors." (PMID 27595989, 2016). "Growth assays showed that loss of CD44 and RHAMM predominantly inhibit anchorage dependent and independent growth of AGL low bladder cancer cells." (PMID 27595989, 2016). "BCSCs were recently isolated in bladder cancer samples with the surface makers (Lineage-CD44+CK5+CK20-), similar to normal bladder basal cells (NBBSc)." (PMID 26143634, 2015). "We previously reported that miR-34a, which seems to be a cancer suppressor miRNA in renal cancer, and sensitized bladder cancer cells to cisplatin by directly targeting CD44." (PMID 26036633, 2015). "CD44-expressing tumor-initiating cells in bladder cancer have been found to confer resistance to cisplatin compared to CD44- negative cells." (PMID 25909217, 2015). "Here, we identified mir-34a as down-regulated in bladder cancer, and verified that microRNA-34a functions as an anti-metastatic microRNA and suppresses angiogenesis in bladder cancer by directly targeting CD44." (PMID 25551284, 2014). "As we know, CD44 have been described as a marker of human bladder cancer stem cells (CSCs), which have been reported to be resistant to therapeutics." (PMID 24423412, 2014). "In this study, we focus on it that microRNA-34a functions as an anti-metastatic microRNA and suppress angiogenesis in bladder cancer by directly targeting CD44." (PMID 25551284, 2014). "Increased miR-34a expression significantly sensitizes bladder cancer cells to cisplatin treatment and inhibits the tumorigenicity and proliferation of cancer cells in vitro and in vivo through targeting CD44." (PMID 24423412, 2014). "Although there are many related research, that microRNA-34a functions as an anti-metastatic microRNA and suppresses angiogenesis in bladder cancer by directly targeting CD44 still need further illuminated." (PMID 25551284, 2014). "Our study defines a major metastasis and angiogenesis suppressive role for mir-34a, a microRNA functions as a tumor suppressor in bladder cancer by directly targeting CD44, which would be helpful as a therapeutic approach to block bladder cancer metastasis." (PMID 25551284, 2014). "Next, we investigated the direct effects of miR-34a on CD44 expression in bladder cancer cell lines; we conducted the miRNA overexpression experiments." (PMID 25551284, 2014). "CD44 was overexpressed in bladder cancer and had a central role in regulating diverse aspects of bladder cancer pathogenesis." (PMID 25551284, 2014).
bladder cancer (continued). "Another report also suggested that HSP90 inhibitors efficiently enhanced the anticancer effect of CDDP on bladder cancer-initiating cells which were isolated based on their CD44 expression status." (PMID 24718854, 2014). "Some splicing events have been reported to be related to bladder cancer using exon arrays, including CD44, CLSTN1 and CTNND1." (PMID 24622401, 2014). "Our study proved that mir-34a functions as an anti-metastatic microRNA and suppresses angiogenesis by directly targeting CD44 in bladder cancer and subsequently suppress CD44 that regulates transcription of a variety of genes in bladder cancer cells." (PMID 25551284, 2014). "A previous study using competitive RT-PCR to detect the expression of CD44 in urine for bladder cancer diagnosis was highly accurate and a potential non-invasive diagnostic marker for bladder cancer." (PMID 23683495, 2013). "HA overexpression is greatly dependent on the CD44, so the regulation of bladder cancer growth, invasion and angiogenesis was proven to occur through the CD44 by HA synthase-1 expression." (PMID 23516416, 2013). "Also, CD44 and HIF signals contribute to cancer stemness and maintaining CSCs in bladder cancer, and the transduced synNotch receptor inhibits both CD44 and HIF signals simultaneously." (PMID 40011711, 2025). "A study showed that urinary CD44 could be used to differentiate an aggressive form of bladder cancer from a low-grade tumor." (PMID 41440277, 2025). "Bladder cancer stem cells (BCSCs), often derived from bladder epithelial stem cells or bladder cancer nonstem cells, exhibit rich clonal homogeneity and mainly express the surface markers CD44, 67LR, and BCMab1." (PMID 41387479, 2025). "CD44 is a receptor on the cell surface for binding extracellular matrix proteins, such as hyaluronic acid (HA), and is recognized as a marker for cancer stem cells in bladder cancer." (PMID 40011711, 2025). "This work suggests a novel mechanism partly explaining the inverse relationship between AR and bladder cancer tumor progression and suggests that AR and CD44 expression may be useful for prognostication and therapeutic selection in primary bladder cancer." (PMID 38539529, 2024). "Taken together, blocking production of HA, one of the main ligands for CD44, inhibits growth of bladder cancer cells in vitro and in mouse xenograft models, supporting the notion that CD44 functioning as a receptor is a driver of bladder cancer growth, progression, and recurrence." (PMID 38539529, 2024). "CD44 was found to be significantly enriched in bladder cancer patients." (PMID 38539529, 2024). "Furthermore, bladder cancer tissues with low LASS2 expression had a higher proportion of stem-like cells (CD44+ALDH1A1+)." (PMID 38191448, 2024). "Liu and colleagues suggested that CD44 is a key regulator of tumor macrophage infiltration, and it may be involved in M2 protumor polarization in bladder cancer." (PMID 38546390, 2024). "Notably, CD44 expression emerged as a significant prognostic indicator, correlating with poorer outcomes in bladder cancer patients." (PMID 39768377, 2024). "And CD44 may promote the progression of bladder cancer by affecting the immunosuppressed M2 macrophages." (PMID 37316699, 2023). "Whether prolonged exposure to mistletoe might be required to induce a CD44 switch from CD44s to CD44v in the bladder cancer cell model requires further investigation." (PMID 37835543, 2023). "UALCAN was used to analyze the expression of CD44 in bladder cancer (BLCA) and normal tissue." (PMID 37316699, 2023). "Binding of USP28 to CD44 standard (CD44s) protein leads to removal of the ubiquitin group from the ubiquitinated CD44s protein, resulting in the stabilization of CD44s protein to mediate the stem-like property of human bladder cancer cells." (PMID 35269796, 2022). "More interestingly, ALDH1A1+ cells were found to be a subtype of CD44+ cells, suggesting that such cells may be the more primitive bladder cancer CSCs." (PMID 35903544, 2022).
bladder cancer (continued). "Therefore, tumor initiation ability of CD44+ cells is confirmed, and CD44 can be used as a sorting marker of bladder cancer stem cells (BCSCs)." (PMID 35342431, 2022). "CD44, as a stem cell marker of bladder cancer could be regulated by NF-κB signaling pathway which played an important role in bladder cancer." (PMID 33573671, 2021). "CD44 is highly expressed across a wide variety of human cancers including bladder cancer." (PMID 32434417, 2020). "Some studies have reported that CD44 is frequently expressed in bladder cancer." (PMID 32434417, 2020). "CD44 expression was reported to be significantly associated with disease failure from multivariate survival analysis, suggesting that CD44 may be a potential marker for predicting disease failure in bladder cancer." (PMID 32434417, 2020). "Studies showed that the polymorphismsin CD44 play a substantial role in the development ofbreast and bladder cancers in the northern Indianpopulation and they may be important as a molecularprognostic markers." (PMID 31376327, 2020). "Therefore, the current study was performed to investigate the relationships of CD44 expression with the clinicopathological features and the prognosis in patients with bladder cancer." (PMID 32434417, 2020). "Our finding suggested that CD44 expression may be correlated with progression, metastasis, and disease failure of bladder cancer." (PMID 32434417, 2020). "Expression level of CD44 in bladder cancer was lower than in normal tissues (P = 0.045)." (PMID 32434417, 2020). "Hence, the correlations between CD44 expression and the clinicopathological features and the prognosis of bladder cancer were investigated." (PMID 32434417, 2020). "Although many studies have reported the role of CD44 expression in bladder cancer." (PMID 32434417, 2020). "Our previous studies indicated that the monoclonal antibody BCMab1 recognized aberrantly glycosylated integrin α3 and could be used in the isolation of human bladder cancer stem cells (BCSCs) when combined with CD44." (PMID 32065779, 2020). "miR-34a targets identified in the context of bladder cancer cells include CD44 and TCF1 and LEF1." (PMID 33114775, 2020). "Further, we identified distinct N-glycosylation pattern of CD44, MGAM, and GINM1 between NMIBC and MIBC patients, which may be associated with disease progression in bladder cancer." (PMID 32922663, 2020). "Indeed, anti-CD44 antibody can induce differentiation and apoptosis in leukemia and bladder cancer cells, while CD133+ cancer cells can be targeted using an anti-CD133 antibody conjugated with cytotoxic drug." (PMID 32974206, 2020). "However, the clinical role of CD44 expression in patients with bladder cancer is still controversial." (PMID 32434417, 2020). "Moreover, further TCGA data demonstrated that expression level of CD44 in bladder cancer was also lower than in normal tissue samples, which was further confirmed from TCGA dataset." (PMID 32434417, 2020). "Therefore, miRNA-34a and CD44 are potential anti-angiogenic and anti-metastatic therapeutic targets in bladder cancer patients." (PMID 29383201, 2017). "To determine whether tumor-initiating cell subpopulations existed in different bladder cancer cell lines, we first isolated CD44-positive cells from seven human bladder cancer cell lines, including T24, 5637, RT4, SW780, UM-UC-3, TCCSUP, and HT-1376." (PMID 29340052, 2017). "Moreover, overexpression of miRNA-34a inhibited angiogenesis and metastasis of bladder cancer cells by targeting CD44." (PMID 29383201, 2017). "Notably, treatment with cisplatin increased CD44-positive bladder cancer cells expressing Oct4, representing cancer stem-like cell subpopulation." (PMID 27244887, 2017). "Since Oct4 is considered a key maintainer of CSC pluripotency, we next explored whether expression of Oct4 and CD44 was increased in bladder cancer cells following cisplatin treatment." (PMID 27244887, 2017).